BCL2L11 (BCL2 like 11)
Diseases named in the same sentence as BCL2L11 in open-access papers (continued):
Sharing a sentence is not in itself a finding about the gene and the disease.
A further 64 diseases each share a sentence with BCL2L11 in 1 paper.